IDH1 (isocitrate dehydrogenase (NADP(+)) 1)
Diseases named in the same sentence as IDH1 in open-access papers (continued):
Sharing a sentence is not in itself a finding about the gene and the disease.
glioma (continued). "Interestingly, the TERT promoter mutation always occurred in the setting of patients with IDH1/2 mutation and this mutation highly correlated with upregulated TERT mRNA expression and tumor grade in adult gliomas." (PMID 26468983, 2015). "And in TCGA samples, 5.9% of grade 3 gliomas with IDH1 mutation/1p19q co-deletion harbored mutations in U2AF2 while no mutations were found in grade 2 gliomas with the same molecular signature." (PMID 26524630, 2015). "On the other hand, IDH1-positive gliomas are relatively rare in the paediatric population." (PMID 25849605, 2015). "To develop a hypothesis regarding the mechanism of enhanced 5-ALA fluorescence in IDH1 mutant malignant glioma cells, we reviewed crosstalk between the TCA cycle and the heme synthesis pathway." (PMID 26008980, 2015). "The IDH1 mutation is observed in 6% of WHO grade IV glioblastomas and 55% of grade III gliomas." (PMID 26008980, 2015). "Alternatively, our data suggested that there existed an under-characterized subset of IDH1/2 wild-type lower-grade gliomas with comparable survival to IDH1/2 mutated gliomas lacking 1p/19q codeletion and TERTp mutation." (PMID 26369702, 2015). "It was revealed that IDH1 mutated glioma was more likely to present a less (or none) contrast enhancement, and a larger tumor size." (PMID 25823012, 2015). "To select candidate metabolites related to enhanced 5-ALA fluorescence in IDH1 mutant malignant glioma cells, we identified three metabolites (citrate, ɑ-KG, and 2-HG) of which the levels were significantly altered in U87MG-IDH1R132H cells after 5-ALA treatment." (PMID 26008980, 2015). "In summary, our results demonstrate that combining IDH1/2 mutation status with Ki-67 expression levels can be used to define five glioma subgroups regardless of the conventional WHO grade." (PMID 26338964, 2015). "In conclusion, this is the first study that investigates the immunohistochemical expression of the IMP3 protein with a correlation with other important parameters (IDH1 mutation and MGMT methylation status) and Ki67 proliferative index in a large series of high-grade gliomas." (PMID 25695077, 2015). "Detection of molecular glioma biomarkers such as MGMT promoter methylation, IDH1/IDH2 mutation, 1p/19q co-deletion, epidermal growth factor receptor (EGFR) amplification and EGFR variant III (EGFRvIII) expression in tumor tissue is increasingly being used in clinical care." (PMID 25720744, 2015). "IDH-1 is now being targeted for therapeutic use for instance by Agios Pharmaceuticals, who are currently moving forward with the drug candidate AG-120 after their tool compound inhibitors were found to be successful in glioma xenografts." (PMID 25312641, 2014). "Alternatively, IDH1/2 wildtype ALGGs that lack a genomic GBM signature should be evaluated for other potential oncogenic drivers, including mutations such as FGFR1 p.K656E, which has been identified in pediatric gliomas." (PMID 25257301, 2014). "IDH1 mutations are present in low but not high-grade gliomas and preferentially occur in young patients with improved prognosis." (PMID 24728830, 2014).
glioma (continued). "Additionally, recent studies uncovered somatic mutations in the two IDH isoforms, IDH1 and IDH2, which occur at high frequencies in cancers, including gliomas, astrocytomas, chondromas and acute myeloid leukemia (AML)." (PMID 25015087, 2014). "In addition to IDH1 mutations, mutations in the homologous gene, IDH2, have also been identified in gliomas, but are much less common than the IDH1 mutations." (PMID 24932255, 2014). "IDH1 mutations can be recognized using a mutation-specific antibody directed against the most common mutation site in WHO II° gliomas, but generally absent in LEAT." (PMID 24858213, 2014). "Indeed, recurrent somatic IDH1 and 2 mutations are found in the vast majority of grade II and III young adult gliomas and secondary GBM." (PMID 25077668, 2014). "The findings support reports that IDH1/2 mutations and MGMT methylation can be used in addition to tumour grade and clinical factors to predict survival in patients with recurrent high grade gliomas when treated with any of the therapy regimes used." (PMID 24952577, 2014). "One could also capture additional glioma-relevant genes like IDH1 and IDH2 by adding probes targeting these genomic regions." (PMID 25608559, 2014). "Similar OS differences in IDH1-mutant versus IDH1-WT tumors were observed for anaplastic astrocytomas, such as 5.4 versus 1.7 years, 6.8 versus 1.6 years, and 7 versus 2 years as well as for low-grade gliomas." (PMID 24511544, 2014). "As grade is a well-known prognostic factor in glioma patients, we first investigated whether distinct tumor subgroups could be distinguished using only TERT promoter and IDH1/2 mutation status within each grade." (PMID 24722048, 2014). "Tumors that did not harbor mutations in either the TERT promoter or IDH1/2 comprised a unique clinical group with a short OS (median OS 17.2 months) that was distinct from TERT promoter mutated gliomas (median OS 11.5 months)." (PMID 24722048, 2014). "The isocitrate dehydrogenase 1 (IDH1) mutation was reported to be a biomarker in the prediction of clinical outcomes for patients with GBM, and patients with IDH1 mutations exhibit better outcome than those with wild-type IDH1 in gliomas." (PMID 24438238, 2014). "Genetic aberrations in IDH1 have been reported in 50–80% of gliomas WHO grade II to IV." (PMID 24868540, 2014). "Given the clinical value of identifying IDH1/2 mutated gliomas, our findings provide a compelling reason to advance IDH1 p.R132H protein negative ALGGs for exome or targeted sequencing of IDH1/2." (PMID 25257301, 2014). "Although they found no mutations in TET2, they identified promoter methylation of TET2 in 5 of 35 low-grade gliomas, whereas low-grade gliomas with IDH1/2 mutations showed no hypermethylation of the TET2 promoter." (PMID 24202321, 2013). "We found that NADP+-dependent isocitrate conversion was not decreased in E478 xenografts as compared to IDHwt glioma, indicating that cells compensate for loss of IDH1 activity by increasing mitochondrial IDH2 activity by inducing mitochondrial biosynthesis." (PMID 24252742, 2013). "This is accompanied by decreased proliferation of IDH1-mutant glioma cells, without causing significant changes in genome-wide DNA methylation levels." (PMID 24077826, 2013). "Mutations in IDH1 and IDH2, frequently found in gliomas and acute myeloid leukemias (AML), are characterized by enzymatic gain of function and subsequent production of hydroxyglutarate, which inhibits several histone demethylases, including H3K9, H3K27, H3K36 and H3K4." (PMID 23356856, 2013). "We have shown consistent IDH1/IDH2 status in the progression of gliomas and lack of association between IDH1mutation and malignant progression." (PMID 23840696, 2013). "D-2HG levels in plasma of tumor-bearing mice were not altered (data not shown) which is in agreement with the recent finding that plasma levels of D-2HG do not correlate with IDH1-mutation status in glioma patients." (PMID 24252742, 2013).
glioma (continued). "The ability to induce a sustained differentiation phenotype in the tumor-initiating subpopulation of IDH1 R132H gliomas may provide a promising therapeutic window of opportunity for tumors with this mutation." (PMID 24077826, 2013). "In contrast, 2-HG was nearly undetectable in tissue obtained from IDH1 wild type glioma controls." (PMID 24077805, 2013). "It relates IDH1(R132MUT) GBMs to lower-grade IDH1(R132MUT) gliomas." (PMID 24202337, 2013). "The predictive value of IDH1 and IDH2 mutations in gliomas remains controversial." (PMID 23894344, 2013). "Additionally in a study published in this issue, treatment of endogenous IDH1 mutant glioma cell lines with hypomethylating agent 5-aza-2'-deoxycytidine was found to drive differentiation in vitro." (PMID 24077805, 2013). "IDH1 mutation was not a predictive marker for malignant progression and it was a potential prognostic marker for gliomas of Chinese patients." (PMID 23840696, 2013). "We are investigating whether the mutant IDH1 is detected in the EVs from blood or cerebrospinal fluid (CSF) of glioma patients." (PMID 26082317, 2013). "Introduction of mutant IDH1 into primary human astrocytes alters specific histone marks, induces extensive DNA hypermethylation, and reshapes the methylome in a fashion that resembles the CpG island methylator phenotype in low-grade gliomas." (PMID 24202337, 2013). "This metabolic adaptation may be in line with the increased dependency of IDH1-mutant gliomas on exogenous glutamine, the low levels of glutamate in IDH1-mutant gliomas and the sensitivity of these tumors to glutaminase inhibitors." (PMID 24252742, 2013). "This is in line with a previous report which demonstrated that xenografting of cultured IDH1 mutant glioma cells hardly results in in vivo tumor growth and is in sharp contrast with our experience with orthotopic xenografting of IDH1wt gliomas in which success rates approach 100%." (PMID 24252742, 2013). "In 2008, IDH1 and IDH2 mutations were first reported in low grade of gliomas and secondary GBM." (PMID 24217114, 2013). "Though many studies demonstrated that IDH1 mutation was an important biomarker in glioma, mechanism of IDH1 mutation in glioma was not yet fully determined." (PMID 23840696, 2013). "As reduced glutathione is essential for scavenging reactive oxygen species (ROS), this may result in increased oxidative stress in IDH1-mutant glioma cells, a phenomenon that will be further augmented by increased mitochondrial density." (PMID 24252742, 2013). "It has been shown by several groups that gliomas with IDH1 mutations are difficult, if not impossible, to culture and propagate in vitro under standard serum-free or serum-containing culture conditions." (PMID 24252742, 2013). "However, subsequent studies reported that IDH1 mutations were detected at much higher frequencies ranged from 60% to 80% in WHO grades II and III gliomas as well as in secondary GBMs." (PMID 22291938, 2012). "Twenty five IDH1 mutations were present in the gliomas tested (23 × R132H, 1 × R132S, and 1 × R132L); no IDH2-mutant tumors were present." (PMID 23267435, 2012). "Heterozygous mutations in IDH2 at Arg172 and at the analogous residue Arg132 in IDH1 are frequently found in grade 2 and 3 gliomas, secondary glioblastomas, and acute myeloid leukemia (AML), but they occur less frequently in primary glioblastomas and other cancers." (PMID 22675360, 2012). "However the occurrence of uncommon inactivating IDH mutations, loss of heterozygosity of IDH in some tumors, and monoallelic expression of IDH1 in some gliomas points to as yet uncharacterized mechanisms of disease associated with IDH dysfunction." (PMID 23267435, 2012).
glioma (continued). "In additional to the traditional criteria for tumour infiltration, we introduced IDH1 into our classification criteria for infiltration to help distinguish LGG from gliosis at the glioma border zone, which is often difficult using traditional histopathological criteria." (PMID 22729482, 2012). "Irrespective of pathology, the incidence of IDH1/2 mutation in gliomas of the frontal origin (73.5%) was significantly higher than that of non-frontal origin (48.5%) (P<0.001)." (PMID 22427879, 2012). "In fact, the test can be conveniently adapted to identify hot spot mutations in other genes and we have successfully utilized ASLNAqPCR to identify IDH1-R132H mutation with high specificity and sensitivity in a series of more than 100 gliomas (data not shown)." (PMID 22558339, 2012). "In IDH1-mutated gliomas, 2-HG accumulates to concentrations of approximately 5–35 mM which is 100-fold higher than that in gliomas without these mutations." (PMID 23162793, 2012). "Our series of microdissected and non-microdissected gliomas confirms both the high frequency and the early time point of IDH1- mutations in glioma development." (PMID 22844452, 2012). "As not all low- grade gliomas featured IDH1- mutations, we presume that tumor- initiating events other than IDH1 alterations exist." (PMID 22844452, 2012). "Recently, many studies have suggested that low-grade gliomas (LGGs, WHO grade 2) including astrocytoma (As), oligodendroglioma (OG) and oligoastrocytoma (OA) display a highly methylated profile, in particular LGGs with mutated IDH1." (PMID 21829728, 2011). "We next tested whether IDH1-R132H, the most common IDH mutant in gliomas, could bind to other IDH1-R132H molecules in cells." (PMID 21326614, 2011). "All collected data suggest that glioma tumour cells with IDH1 mutation cannot be propagated in vitro in conditions suitable for survival of normal human cells or glioma cells without IDH1 mutation." (PMID 21326241, 2011). "R132H is the most common IDH1 substitution in gliomas, followed by R132C, R132S, R132L, and R132G." (PMID 21326614, 2011). "Fifth, the current meta‐analysis did not obtain information on IDH1 or other glioma‐associated mutations that could alter the inflammatory status." (PMID 41503680, 2026). "Per the WHO Classification of Tumours (5th edition), essential criteria for this diagnosis include a diffuse glioma with mitotic activity occurring in a child or young adult, absence of mutations in IDH1/2 and H3 genes, and a confirmatory methylation profile or other key molecular features." (PMID 40610013, 2026). "T1ρ may thus serve as a faster, non‐invasive biomarker of IDH1 status in glioma." (PMID 41436375, 2026). "Furthermore, LSM2 expression was significantly higher in gliomas with 1p/19q non-deletion (494 cases) than in those with 1p/19q co-deletion (169 cases) (p < 0.001), as well as in IDH1-mutant gliomas (429 cases) compared to IDH1 wild-type cases (233 cases) (p < 0.001)." (PMID 40365337, 2025). "The selective synergy observed in IDH1 WT backgrounds, particularly with the compound 2/TMZ combination, suggests that IDH1 mutation status modulates the efficacy of RNaseH2 inhibition, meriting further investigation in genetic models that further reflect glioma diversity." (PMID 41285884, 2025).
glioma (continued). "Similarly, the genomic distances between glioblastoma and oligodendroglioma (median JD: 0.118) and between IDH1/2-mutant astrocytoma and oligodendroglioma (median JD: 0.088) were greater than the genomic heterogeneity within each respective glioma subtype (all P < .001)." (PMID 39164213, 2025). "In particular, no IDH1 or IDH2 mutations were detected, excluding IDH1/2-mutant gliomas." (PMID 40234994, 2025). "Molecularly defined IDH1/2-mutant astrocytomas (grades 2–4) showed the greatest heterogeneity in their original histopathologic classifications—55.0% were previously classified as astrocytomas, 24.8% as glioblastoma, 13.4% as other gliomas, and 6.8% as oligodendrogliomas." (PMID 39164213, 2025). "Notably, the C2 NUSAP1+ glioma cell subpopulation was exclusive to the IDH1 wildtype group." (PMID 39975552, 2025). "However, PD-L1 inhibitors may have reduced efficacy in IDH1 (R132H)-mutant gliomas, as suggested by the inverse correlation between IDH1 (R132H) expression and PD-L1 levels." (PMID 39906459, 2025). "Scenario 0 represents actual information about the patient: young patient in their 20s with low grade glioma with unknown referral method, no mutations in gene IDH1 and no treatment with alkylating agents." (PMID 40353995, 2025). "Notably, some histologically low-grade gliomas exhibit aggressive phenotypes due to CDKN2A/B homozygous deletions or H3F3A mutations, while certain high-grade tumors with IDH1/2 mutations may benefit from low-intensity therapies." (PMID 41377022, 2025). "Due to these survival benefits, IDH1/2 mutations are not only valuable prognostic biomarkers but are also being investigated as potential therapeutic targets, with IDH inhibitors currently in clinical trials aiming to improve survival for this subset of glioma patients." (PMID 39767571, 2024). "Furthermore, the Idh1 and Idh2 mutations identified in rat gliomas did not have homology to known human variants in COSMIC database." (PMID 38232086, 2024). "In grade 3 gliomas (n = 26), 22 cases (84.6%) showed IDH1 mutations, and no EGFR-amp was observed." (PMID 38893240, 2024). "In addition, the expression of IGFBP3 was also increased in gliomas, and associated with IDH1/2 mutations status, histology and tumor grade, it was suggested that IGFBP3 may be a prospective new target for the therapy of glioma." (PMID 38326861, 2024). "Interestingly, while IDH1 mutations may be lost in recurrent GBM, they often persist in recurrent gliomas and may be the sole initial mutation driving the recurrence." (PMID 39529768, 2024). "Other examples are ivosidenib, an isocitrate dehydrogenase-1 (IDH1) inhibitor, and enasidenib, an IDH2 inhibitor, which effectively targets relapsed or refractory acute myeloid leukaemia with IDH1/2 mutations but that are not effective in gliomas bearing these mutations." (PMID 38549846, 2024). "Furthermore, the lack of information on the patients’ IDH1 mutation status in the TCGA lower-grade glioma dataset made it difficult to classify patients according to the 2021 CNS WHO classification." (PMID 38672212, 2024).